FYN (FYN proto-oncogene, Src family tyrosine kinase)
Diseases named in the same sentence as FYN in open-access papers (continued):
Sharing a sentence is not in itself a finding about the gene and the disease.
atherosclerosis (2 papers, 2024 to 2025). A disease characterized by the build-up of fatty material and calcium deposition in the arterial wall resulting in partial or complete occlusion of the arterial lumen. "In conclusion, our finding suggests that KDM2A regulates phenotypic alterations in macrophages through the transcriptional activation of FYN during the development of atherosclerosis." (PMID 40303308, 2025). "The current study provides the novel role of KDM2A in macrophage inflammatory response of atherosclerosis through transcriptional regulation of FYN." (PMID 40303308, 2025). "Recent evidence has suggested a link between FYN and the oxidative response, which plays a critical role in driving macrophage M1 phenotypic transformation, thereby contributing to the development of atherosclerosis 68-70." (PMID 40303308, 2025).
cholangiocarcinoma (2 papers, 2023). A carcinoma that arises from the intrahepatic biliary tree (intrahepatic cholangiocarcinoma) or from the junction, or adjacent to the junction, of the right and left hepatic ducts (hilar cholangiocarcinoma). "FYN knockdown or downregulation inhibits the migration and invasion of cholangiocarcinoma cells." (PMID 36740671, 2023).
cognitive deficits (2 papers, 2020 to 2023). "In addition, overexpression of FYN in an AD mouse model accelerated synapse loss and cognitive deficits, with loss of FYN reversing these AD-related sequelae." (PMID 31951614, 2020). "We discovered that ZDHHC21 p.T209S contributed to AD by enhancing the palmitoylation of FYN and APP, resulting in AD pathology and synaptic dysfunction, ultimately causing cognitive impairment." (PMID 37365538, 2023).
E. coli infection (2 papers, 2015 to 2023). "However RRMS clinic subtype patients also show an increase in the ACTB, KRT18, FYN, TUBA4A, NCL, CTNNB1 proteins which are a part of pathogenic E. coli infection pathway, which induce the mobilization of inflammatory cells." (PMID 25942430, 2015).
esophageal squamous cell carcinoma (2 papers, 2020 to 2023). Esophageal squamous cell carcinoma (ESCC) is a type of esophageal carcinoma (EC) that can affect any part of the esophagus, but is usually located in the upper or middle third. "LINC00152 promotes esophageal squamous cell carcinoma (ESCC) proliferation by downregulating miR-153-3p and promoting FYN expression." (PMID 36740671, 2023). "FYN is a downstream target of miR-153-3p, and the downregulation of miR-153-3p levels promotes FYN expression for esophageal squamous cell carcinoma (ESCC) proliferation." (PMID 36740671, 2023).
Insulin resistance (2 papers, 2013 to 2025). Increased resistance towards insulin, that is, diminished effectiveness of insulin in reducing blood glucose levels. "The downregulation of src kinase FYN seems to be a counteracting compensatory mechanism as this protein is important in IFN gamma action, in TNF alpha induced COX2 expression and in adipose tissue - mediated inflammation leading to insulin resistance." (PMID 24303025, 2013).
ischemic stroke (2 papers, 2022 to 2023). A stroke disorder caused by obstruction of blood flow to the brain, due to thrombotic (local blood clot formation) or embolic (due to a blood clot or other material traveling from another site) event. "In a concordant finding, a bioinformatics analysis of inflammation associated competing endogenous RNA network in ischemic stroke has reported FYN and PXN among the most significantly enriched modules from the hub genes." (PMID 35250546, 2022). "In a rabbit, increased expression of FYN gene after ischemic stroke has been documented, and the authors suggested that GP6 induced activation of FYN initiated phosphorylation events eventually accelerating platelet adhesion." (PMID 35250546, 2022). "A recent study has demonstrated that Gp6 contributes to atherosclerotic cerebral ischemic stroke development by activating the FYN-PKA-pPTK2/FAK1 signaling pathway, indicating the critical roles of Gp6 in ischemic stroke." (PMID 37229192, 2023). "FYN is a type of Src Family Kinase (SFK) gene, that code for a non-receptor protein tyrosine kinase and SFK inhibitors have shown protective action against ischemic stroke in animals." (PMID 35250546, 2022).
lung adenocarcinoma (2 papers, 2016 to 2019). A carcinoma that arises from the lung and is characterized by the presence of malignant glandular epithelial cells. "BMP4 depletion by miR-200 inhibits tumorigenesis and metastasis in lung adenocarcinoma cells and finally FYN promotes cancer progression through epithelial-to-mesenchymal transition." (PMID 31027181, 2019). "Three genes, PTCH1, CTNNB1, and FYN, have been predicted to contribute to the initiation and progression of lung adenocarcinoma in all the six gene sets." (PMID 27412431, 2016).
mastitis (2 papers, 2017 to 2020). Inflammation of breast tissue during lactation or postpartum due to an obstructed duct or infection. "Additionally, some of the highly connected genes belonging to this module have been found by others to be related to mastitis development, immune response or mammary gland development including FYN, CDH11, CAV1, F11R, ZEB1, ERBB2, and ERBB3." (PMID 32754201, 2020).
prion disease (2 papers, 2020 to 2023). A transmissible disease that is caused by a protein that is able to induce abnormal folding of normal cellular proteins, leading to characteristic spongiform brain changes, which are associated with neuronal loss without an inflammatory response. "Among genes associated with prion diseases, the over-expression of some (PSEN1, FYN, SMC3, CHD2, EP300) in late-cycle could be rationalized by considering related proteins in humans, which, when expressed in their monomeric (soluble) form, exert protective functions for cellular homeostasis." (PMID 37048113, 2023).
psoriasis (2 papers, 2013 to 2019). An autoimmune condition characterized by red, well-delineated plaques with silvery scales that are usually on the extensor surfaces and scalp. "CCNA2, TFDP1 and MECOM might play role in the hyperproliferation of keratinocytes, whereas FYN may be involved in the disturbed immunity in psoriasis." (PMID 24303025, 2013). "Many DEG-coded proteins (CCNA2, FYN, PIK3R1, CTGF, F3) and transcription factors (AR, TFDP1, MEF2A, MECOM) were identified as central nodes, suggesting their potential role in psoriasis pathogenesis." (PMID 24303025, 2013).
pulmonary fibrosis (2 papers, 2023). Chronic progressive interstitial lung disorder characterized by the replacement of the lung tissue by connective tissue, leading to progressive dyspnea, respiratory failure, or right heart failure. "Of these six master regulators, three master regulators are found to be associated with pulmonary fibrosis (ERBB2, EGFR and FGFR2) and one with inflammation (FYN)." (PMID 37206915, 2023). "By searching the 18 candidate hub genes in GeneCards database, we found that CAV1 and PECAM1 were specifically expressed in lung tissues, BMP4 and VEGFA were related to angiogenesis, FYN and SPP1 were related to immunity or inflammation, and COL1A1 was closely associated with pulmonary fibrosis." (PMID 37794454, 2023). "Among those genes, we found that CAV1 and PECAM1 were specifically expressed in lung tissues, BMP4 and VEGFA were related to angiogenesis, FYN and SPP1 were related to immunity or inflammation, and COL1A1 was closely associated with pulmonary fibrosis according to the GeneCards database." (PMID 37794454, 2023).
synovial sarcoma (2 papers, 2024 to 2025). "We find that exposure of synovial sarcoma cells to FK228, a potent HDAC1/2 inhibitor, leads to the induction of FYN mRNA and protein expression which could render synovial sarcoma cells resistant to growth inhibition after loss of SS18-SSX function." (PMID 39045458, 2024). "The best evidence for this view of SS18-SSX function is that genetic or pharmacologic inhibition of SS18-SSX reactivates its target gene FYN and promotes FYN protein accumulation in synovial sarcoma cells." (PMID 40296913, 2025). "But one exception is the proto-oncogene, FYN, which shows increased expression in synovial sarcoma cells after SS18-SSX depletion." (PMID 40296913, 2025). "In support of this notion, we find that blockade of FYN activity synergistically enhances HDACi action to reduce synovial sarcoma cell proliferation and migration." (PMID 39045458, 2024). "In this study, we identify the proto-oncogene FYN as a new direct target of SS18-SSX in human synovial sarcoma cells." (PMID 39045458, 2024). "Our results support a role for FYN in attenuation of anti-cancer activity upon inhibition of SS18-SSX function and demonstrate the feasibility of targeting FYN to improve the effectiveness of HDACi treatment against synovial sarcoma." (PMID 39045458, 2024). "In keeping with this view, we show that combination of FK228 with the FYN inhibitor PP2 results in a synergistic treatment effect in synovial sarcoma cells (right)." (PMID 39045458, 2024). "Notably, FYN itself is a druggable target, and exposure of synovial sarcoma cells to the small molecule PP2 (a potent FYN inhibitor) brings about the enhanced efficacy of HDAC inhibitor treatment." (PMID 40296913, 2025). "Finally, in terms of biological regulation and function of FYN in synovial sarcoma, some limitations should be considered." (PMID 39045458, 2024). "Since FYN is known to promote metastasis in many types of cancer, we also asked whether FYN plays a similar role in synovial sarcoma." (PMID 39045458, 2024). "Although the biological function of FYN in synovial sarcoma remains unknown, previous studies have established a critical role for the FYN kinase in promoting cell proliferation and migration during cancer development." (PMID 39045458, 2024). "Overall, our results potentially explain the clinical observation that HDACi treatment alone elicits limited anti-cancer activity in synovial sarcoma patients, and provide a biological rationale for blocking FYN function to improve HDACi action in synovial sarcoma treatment." (PMID 39045458, 2024). "Collectively, these observations reinforce the involvement of FYN in synovial sarcoma cell response to HDACi treatment, and suggest that inhibition of FYN activity may be a therapeutic strategy to enhance the effectiveness of HDACi treatment for synovial sarcoma." (PMID 39045458, 2024). "Here, we identify the proto-oncogene FYN as a new SS18-SSX target gene and examine its relation to synovial sarcoma therapy." (PMID 39045458, 2024). "Moreover, we have explored the therapeutic relevance of the FYN inhibitor PP2, which synergistically interacts with FK228 and improves its efficacy in inhibiting synovial sarcoma cell proliferation and migration." (PMID 39045458, 2024). "FYN is a tyrosine kinase that promotes cancer growth, metastasis and therapeutic resistance, but SS18-SSX appears to negatively regulate FYN expression in synovial sarcoma cells." (PMID 39045458, 2024). "Therefore, at least in part, by blocking FYN activity, PP2 synergizes with FK228 to reduce synovial sarcoma cell migration." (PMID 39045458, 2024). "This implies that FYN accumulation, following inhibition of SS18-SSX, could contribute to synovial sarcoma cell survival in a fusion oncogene-independent manner (left)." (PMID 39045458, 2024).
synovial sarcoma (continued). "In a cell viability assay, addition of PP2 without the HDACi FK228 did not exhibit robust anti-synovial sarcoma effect, in keeping with the limited amount of FYN protein present in SYO-1 cells." (PMID 39045458, 2024). "If so, FYN upregulation may enable synovial sarcoma cells to survive without the need for the presence of SS18-SSX." (PMID 40296913, 2025). "Our work has identified the proto-oncogene FYN as a direct target of SS18-SSX and shown that suppression of SS18-SSX by a potent HDAC inhibitor (FK228) increases FYN expression levels, which may in turn reduces the treatment response of synovial sarcoma cells." (PMID 39045458, 2024). "Thus, it seems likely that FYN downregulation in synovial sarcoma is mediated by SS18-SSX regardless of its fusion type." (PMID 39045458, 2024). "Given the ability of SS18-SSX to negatively regulate FYN expression, it would not be surprising, if FYN activation in response to SS18-SSX-targeted therapy served as a poor prognostic factor for synovial sarcoma." (PMID 40296913, 2025).
thyroid cancer (2 papers, 2023). "FYN is upregulated in thyroid cancer at both mRNA and protein expression levels, which promotes cell proliferation and inhibits apoptosis in thyroid cancer." (PMID 36740671, 2023). "Both the mRNA and protein levels of FYN are upregulated in thyroid cancer, which promotes cell growth and inhibits apoptosis." (PMID 37324495, 2023). "In thyroid cancer, FYN can also control tumor cell migration and invasion." (PMID 36740671, 2023).
uveal melanoma (2 papers, 2014 to 2020). A melanoma derived from melanocytes of the uveal tract. "Several genes, such as HTR2B, CHL1, the ZNF family, YWHAZ and FYN provide potential candidates for distinguishing between uveal melanoma whether contain liver metastases in the future." (PMID 24597767, 2014). "YWHAZ and FYN were identified as key genes in uveal melanoma liver metastases and play crucial roles in cell proliferation, which may be related to the higher incidence of metastases in uveal melanoma." (PMID 24597767, 2014).
abortion (1 paper, 2022). the ending of pregnancy by removing a fetus or embryo before it can survive outside the uterus. "Studies have demonstrated that FYN expression, which is elevated at the fetomaternal interface of abortion-prone mice and RPL patients, plays a role in the regulation of fetomaternal immune tolerance by encouraging the expansion of Th17 cells and the expression of proinflammatory factors." (PMID 35991164, 2022).
acinar adenocarcinoma (1 paper, 2015). "Although the PCa cell lines included in the CCLE were characterized with low expression of FYN, when compared to most of the NE cell lines, this was not unexpected as the majority of cell lines used in PCa research are of an acinar adenocarcinoma phenotype." (PMID 26624980, 2015).
age (1 paper, 2023). A temporal measurement of the time period elapsed since an identifiable point in the life cycle of an organism. "In addition, an age-related increase in palmitoylated FYN in the frontal cortex is reportedly associated with poorer reference memory and/or executive functions, suggesting that a perturbation in palmitoylation may contribute to age-related cognitive decline." (PMID 37365538, 2023).
alcohol use disorder (1 paper, 2025). "Therefore, additional research is needed to confirm therelationship between the FYN gene and alcohol use disorder in each sexthrough an accurate study of the function of the meaningful SNPs described inthis study." (PMID 40110380, 2025).
angioimmunoblastic T-cell lymphoma (1 paper, 2016). A mature T-cell non-Hodgkin lymphoma, characterized by systemic disease and a polymorphous infiltrate involving lymph nodes and extranodal sites. "One of the two cases of angioimmunoblastic T-cell lymphoma demonstrated known pathogenic mutations in RHOA and FYN, proteins involved in T-cell motility and proliferation and TCR signaling." (PMID 27203213, 2016).
atopic dermatitis (1 paper, 2024). "Given the central role of the IKAROS/FYN axis in Th2 polarization, it is tempting to speculate that IKAROS has a role in atopic diseases such as atopic dermatitis and that IKAROS depletion could also be beneficial." (PMID 38885295, 2024).
autism (1 paper, 2023). Persistent deficits in social interaction and communication and interaction as well as a markedly restricted repertoire of activity and interest as well as repetitive patterns of behavior. "More notably, LAMP1 also interact with ITGAL, FYN and FERMT3 which were dysregulated in our blood biomarker screening results, suggesting that these proteins involved in focal adhesion and immune regulation may play a vital role in autism." (PMID 37640746, 2023).
autoimmune disease (1 paper, 2023). A disorder resulting from loss of function or tissue destruction of an organ or multiple organs, arising from humoral or cellular immune responses of the individual to their own tissue constituents. "FYN was a member of the tyrosine kinase gene family, which has been linked to hepatitis and autoimmune diseases." (PMID 36945884, 2023).
Autoimmunity (1 paper, 2023). The occurrence of an immune reaction against the organism's own cells or tissues. "FYN was found to regulate autoimmunity by binding to B-lymphocyte surface antigen CD19 and interacting with immunoglobulin superfamily member CD147." (PMID 36672292, 2023).
bladder cancer (1 paper, 2023). "Additionally, KLF5 binds to the FYN promoter region to induce its transcription, and overexpression of FYN improves lamellar pseudopod formation and migration in bladder cancer cells in which expression of KLF5 is reduced." (PMID 36740671, 2023). "The expression of FYN by KLF5 can increase tumor invasion and cell migration in bladder cancer." (PMID 36740671, 2023).
breast tumors (1 paper, 2023). "Hyperphosphorylation of autophosphorylation site tyrosine in FYN was detected in protein tyrosine phosphatase N23 (PTPN23)-deficient breast cancer tumors, confirming that FYN could be a therapeutic target for PTPN23 heterozygous or pure deletion breast tumors." (PMID 36740671, 2023).
Cerebral ischemia (1 paper, 2025). Restriction of arterial blood supply to the brain associated with insufficient oxygenation to support the metabolic requirements of the tissue. "Also, FTO overexpression can inhibit neuronal ferroptosis by suppressing Src-like protein-tyrosine kinase (FYN) expression and dynamin-related protein 1 (Drp1) activity in cerebral ischemia/reperfusion (I/R) injury." (PMID 40712780, 2025).
chlamydial infection (1 paper, 2015). "During chlamydial infection, the Src kinase FYN has been shown to be essential for sphingomyelin trafficking to the Ctr inclusion." (PMID 25906164, 2015).
cognitive decline (1 paper, 2023). "We also observed that learning and memory were seriously impaired in ZDHHC21T209S/T209S mice, suggesting that activation of FYN signaling induced by the ZDHHC21 mutation was closely associated with cognitive decline." (PMID 37365538, 2023).
diffuse large B-cell lymphoma (1 paper, 2023). "FYN is regulated by miR-431-5p in diffuse large B-cell lymphoma (DLBCL)." (PMID 36740671, 2023).
epilepsy (1 paper, 2017). A brain disorder characterized by episodes of abnormally increased neuronal discharge resulting in transient episodes of sensory or motor neurological dysfunction, or psychic dysfunction. "Participating in mTOR signaling pathway, though the detailed mechanism of the pathology of FYN initiated epilepsy has not been fully revealed, our predicted gene FYN may definitely be an epilepsy associated gene." (PMID 28255556, 2017).
glomerular diseases (1 paper, 2016). "We checked the most important 4 genes YWHAZ, ACTB, APC, and FYN in differentially regulated genes list and found that they were all regulated in at least 3 glomerular diseases, especially the APC was regulated in all 5 glomerular diseases." (PMID 27227331, 2016).
Granuloma (1 paper, 2019). A compact, organized collection of mature mononuclear phagocytes, which may be but is not necessarily accompanied by accessory features such as necrosis. "Among the enrichment score-driving critical genes of the TCR signaling, the levels of transcripts for ITK and its signaling components such as LCK, GRB2, SLP76, NCK1, FYN, and PLCG are significantly upregulated in caseated granulomas compared to uninvolved lung tissue." (PMID 32038633, 2019).
hemangioma (1 paper, 2020). A benign vascular lesion characterized by the formation of capillary-sized or cavernous vascular channels. "FYN is involved in many types of tumor progression, including hemangiomas." (PMID 33519918, 2020).